FAP (fibroblast activation protein alpha)
Diseases named in the same sentence as FAP in open-access papers (continued):
Sharing a sentence is not in itself a finding about the gene and the disease.
tumor (continued). "However, one of the concerns associated with the BiTEs is the off-target toxicity due to the engaging of native T cells’ CD3 antigen and FAP on non-tumor fibroblasts." (PMID 34177890, 2021). "Moreover, adoptive transfer of FAP-specific chimeric antigen receptor to T cells proved to be effective in restraining tumor growth in preclinical models." (PMID 34305902, 2021). "Finally, we interrogated the GSE39396 database, which includes a wide range of cell types: epithelial (EpCAM+), endothelial (CD31+), leukocytes (CD45+), and CAFs (FAP+) isolated by FACS from tumor biopsies." (PMID 33802791, 2021). "In addition, FAP has been found to promote immunosuppression via myeloid-derived suppressor cell (MDSC) recruitment, Tregs, and tumor-associated macrophage (TAM) generation." (PMID 35155199, 2021). "We explored whether nintedanib might affect the number of FAP+ CAFs in B16-F10 tumours by performing flow cytometric analysis." (PMID 33299131, 2021). "The immune suppression caused by FAP+ CAF is mediated by the CXCL12 receptor CXCR4 that excludes T cells from the tumor." (PMID 34094963, 2021). "Interestingly, FAP acts as a tumor suppressor in melanocytic cells that abrogates tumorigenicity through regulation of cell proliferation and survival." (PMID 33959121, 2021). "Furthermore, this study showed that FAP-targeting is potentially superior to [18F]2-fluoro-2-deoxyglucose ([18F]FDG) in PET imaging for many important tumor entities, such as breast, lung, head-and-neck or colorectal cancers." (PMID 34830898, 2021). "The findings above indicate that the PI3K/AKT and RAS/ERK signaling pathways may participate in FAP downstream regulation to promote tumor cell proliferation, migration and invasion, but the downstream regulation may differ in various cancers." (PMID 34068501, 2021). "In multiple cancers, FAP has been proven to play an important role in tumor growth via promotion of tumor proliferation and invasion, and two hypotheses regarding FAP regulation have been proposed." (PMID 34068501, 2021). "FAP staining was visible in both tumor center and tumor front in all 19 cases." (PMID 32733792, 2020). "In mRCC models, CAFs have been shown to recruit macrophages leading to remodeling of the tumor microenvironment and, via signaling through fibroblast activation protein-a (FAP), may promote more aggressive tumor behavior." (PMID 33202724, 2020). "While early results of FAP-specific PET are available for a variety of different tumor entities, the results, albeit promising, should at this stage still be considered as hypothesis-generating." (PMID 32942573, 2020). "It is known that FAP inhibition can decelerate tumor growth." (PMID 33096754, 2020). "Furthermore, some of the perivascular FAP+ cells observed in tissue sections had a nuclear morphology more resembling tumor cells than pericytes, and sometimes were located a considerable distance away from the vessel, arguing against a pericyte identity." (PMID 33082953, 2020). "Likewise, liposomes bearing the mEdg’scFv (Bi-FAP/mEnd-IL and mEnd-IL) should be taken up by the tumor vascular endothelial cells." (PMID 32316521, 2020). "Although breathing movements of the mouse partially distorted the image on the supplementary video, a rapid uptake of Bi-FAP/HER2-IL by tumor cells and pericytes located close to tumor vessels was evident in an intense green fluorescence of the liposomal phospholipid, NBD-DOPE." (PMID 33076292, 2020). "Therefore, in the in vivo situation the bispecific Bi-FAP/HER2-IL should target the tumor cells (based on HER2 or human FAP), TAFs (based on murine FAP of host mouse), and TAMs (based on phagocytosis)." (PMID 33076292, 2020). "Furthermore, FAP positivity in CAFs and concomitant nuclear expression of BCAT in neoplastic cells from the tumor margins were independently associated with a higher risk of metastasis and with worse CSS and DFS of conventional adenocarcinoma patients." (PMID 32428869, 2020).
tumor (continued). "Based on data showing immune control of tumor growth and effectiveness of immune checkpoint inhibitors after FAP inhibition in a KPC mouse model, FAP inhibition is currently being explored in association with pembrolizumab (anti-PD1) (NCT04171219, NCT03910660, NCT04007744)." (PMID 33066357, 2020). "Thus, the larger the tumour, the higher the FAP positive staining, both at the centre and at the edge of the tumour." (PMID 33207686, 2020). "Additionally, FAP ISH analyses showed strong enrichment in the stroma of excluded tumours (bottom row)." (PMID 33149148, 2020). "The FAP-high CAF subtype, instead of the FAP-low subtype, was found to aggressively enhance tumor progression and negatively influence patient outcomes, which shed light on therapeutic strategies involving CAF modulation to consider CAF status in patient selection." (PMID 32850861, 2020). "Thus, the tumor front showed high FAP expression in high histological grade tumors and in all the stages of local invasion (pT)." (PMID 32428869, 2020). "Ex vivo imaging of the FAP+ tumor and organs was also performed to investigate the effects that attenuation and scattering of Cerenkov radiation may have had on the observed imaging results obtained with whole animals." (PMID 32806623, 2020). "The data of this study are clearly promising and may open new applications for noninvasive tumor characterization via FAP-targeting approaches." (PMID 33096754, 2020). "Despite these differences, FAP expression in the primary tumor center and border positively correlated with FAP expression in both lymph nodes (Spearman Rho r=0.166, p=0.028; and r=0.24, p=0.002; respectively) and distant liver metastases (r=0.279, p=0.007; and r=0.256; p=0.016 respectively)." (PMID 32428869, 2020). "Sections of 151 HGSOC patients’ tumor tissues in different stages were stained with FAP-antibody." (PMID 33109151, 2020). "We also compared differences in the expression of FAP between tumour centre and border of RCCs." (PMID 33207686, 2020). "Hence, in the in vivo situation, only the stromal fibroblasts which express murine FAP and the tumor endothelial cells which express the murine endoglin should take up and activate the liposomes." (PMID 32316521, 2020). "Interestingly, flow cytometric analysis of dissociated tumor tissue revealed that almost all tumor cells in which FAP was detected also co‐expressed the CD90 (Thy‐1) surface antigen." (PMID 33082953, 2020). "Recent evidence suggested that FAP in CAFs could also play a critical role in regulating antitumor immune response by inducing tumor-promoting inflammation." (PMID 32733792, 2020). "The increased expression of FAP at the invasive front of tumours may contribute to this invasive behaviour." (PMID 33207686, 2020). "CLI discriminated between FAP+ (tumor) and FAP− (muscle) tissues and FAP+ tumors of varying sizes." (PMID 32806623, 2020). "Furthermore, higher FAP expression is seen in invasive areas of tumours such as tumour borders and microscopic tumour cell protrusions, also known as invadopodia." (PMID 32447444, 2020). "However, both the identity and role of FAP+ stromal or CAF-like cells in the GBM tumor microenvironment are poorly understood." (PMID 33308315, 2020). "In addition, FAP is considered as a potential biomarker in certain tumor diagnosis and progression due to its protumorigenic specificity in both enzymatic and non-enzymatic manners." (PMID 33109151, 2020). "Thus, we elucidated the potential of bispecific liposomes targeting the fibroblast activation protein (FAP) on tumor stromal fibroblasts, together with endoglin which is overexpressed on tumor neovascular cells and some neoplastic cells." (PMID 32316521, 2020). "Thus, we are convinced that the Bi-FAP/mEnd-IL, similar to the monospecific liposome formulations represents a potent tool for the detection of tumor margins and metastatic tissues during surgical interventions." (PMID 32316521, 2020).
tumor (continued). "Our results support the well-known role of FAP in promoting tumor growth and invasion." (PMID 32733792, 2020). "We stratified tissue FAP expression and plasma levels by clinical parameters tightly related to tumour aggressiveness such as Fuhrman histological grade, tumour size, local invasion (pT), presence/absence of affected lymph nodes (N), and time of presentation of distant metastasis (M)." (PMID 33207686, 2020). "Thus, the Bi-FAP/HER2-IL accumulation and cargo release was based predominantly on FAP-directed binding, and enhanced a maximum tumor fluorescence signal at 26 h post-injection." (PMID 33076292, 2020). "Taken together, our results suggest that FAP may contribute to the poor prognosis of CRC by modulating the tumor microenvironment not only by driving angiogenesis but also by promoting a more protumorigenic environment." (PMID 32733792, 2020). "Interestingly, the greatest tumor regression was shown after treatment with the engineered vaccinia viruses encoding scABs targeting both VEGF and EGFR (GLV-1h444), or VEGF and FAP (GLV-1h446)." (PMID 33167307, 2020). "Therefore, new IHC analyses combining FAP with other CAF-related proteins in larger tumour series are necessary to gain in sensitivity and to corroborate the usefulness of these biomarkers as new diagnostic tools." (PMID 33207686, 2020). "Interestingly, the FAP-IL led to a gradual, but persistent increase in tumor fluorescence intensity over time (FAP-IL), which resulted in TBRs in the range 4–6, as from 10 h post injection (FAP-IL)." (PMID 32316521, 2020). "Interestingly, live imaging of SKBR3 tumor revealed a deep penetration of Bi-FAP/HER2-IL shortly after injection, and also exposed the influence of the HER2’scFv on binding and cargo-release of the bispecific liposomes in vivo." (PMID 33076292, 2020). "Thereby, the tumor fluorescence in the FAP-IL group increased slowly over time and reached a maximum approximately 26 h after injection, before slightly decreasing in intensity (FAP-IL)." (PMID 32316521, 2020). "Furthermore, plasma sFAP levels from patients with FAP-negative RCCs were very similar to those in patients with FAP-positive tumours." (PMID 33207686, 2020). "Furthermore, the expression of this protein in CAFs of the tumour stroma, together with its absence from most normal tissues of the body, points to FAP as a very promising target not only for FAP-targeted therapies but also for molecular imaging." (PMID 33207686, 2020). "The presence of lymphovascular invasion was significantly associated with high frequency of FAP-positive cells in tumor center (p = 0.04) but not in tumor front." (PMID 32733792, 2020). "Thus, the overall accumulation of the Bi-FAP/mEnd-IL in the FAP-expressing tumor model increased persistently over time and was still very high 48 h post injection." (PMID 32316521, 2020). "In CRC, previous studies reported the detection for FAP in more than 93% of the tumor." (PMID 32733792, 2020). "Thus, we expected the Bi-FAP/mEnd-IL to simultaneously target the tumor cells (based on human FAP), TAFs (based on murine FAP of host mouse), tumor vasculature (based on murine endoglin) and TAMs (based on phagocytic uptake)." (PMID 32316521, 2020). "Moreover, since administration of excess of FAP targeting ligand (FL) was found to block the tumor uptake of FL-L1-S0456, it can be concluded that tumor accumulation of FL-L1-S0456 is FAP-mediated." (PMID 32483418, 2020). "We validated previous results in a new series of CCRCCs, and the association between FAP positivity and worse prognosis was confirmed, regardless of the area of the tumour in which the protein was expressed." (PMID 33207686, 2020). "Whether the FAP+ tumor cells have a unique function, or represent a particular differentiation state, in comparison with the FAP‐negative fraction is presently unclear." (PMID 33082953, 2020).
tumor (continued). "Indeed, some of the available studies provided direct evidence that the depletion of FAP-positive CAFs leads to an enhanced anti-tumor immunity." (PMID 31659499, 2019). "However, another study showed little efficacy of a FAP CAR in a syngeneic mouse model using multiple tumor types and observed lethal toxicity, which was attributed to FAP expression on bone marrow-derived stem cells (BMSCs)." (PMID 30804938, 2019). "Another promising approach to augment CAR T cell infiltration into tumor sites is the development of a CAR targeting FAP (fibroblast activation protein), which is expressed on multiple types of stromal cells that are associated with nearly all epithelial tumors." (PMID 30804938, 2019). "The degree of desmoplasia was found to be reduced in highly desmoplastic lung cancer xenografts, with a marked disruption of adenocarcinoma ductal-like structure of the tumor nodules, a decrease in collagen and fibronectin content, and an increase in necrosis in FAP-CAR T cell-treated tumors." (PMID 30987642, 2019). "The bispecific, tetravalent fibroblast-activation protein (FAP)-TRAIL-R2 antibody, RG7386, targets cancer-associated fibroblasts in the tumour stroma and TRAIL-R2 on tumour cells simultaneously thereby inducing higher-order clustering and apoptosis induction in vitro and animal models." (PMID 30935038, 2019). "These could be used either to design prodrugs which are activated specifically at the tumor site by the FAP activity or selective enzyme inhibitors." (PMID 31659499, 2019). "We could show that cisplatin treatment significantly reduced the FAP activity of the plasma of 4T1 tumor bearing mice." (PMID 31881770, 2019). "Fibroblast activation protein (FAP) is highly expressed in the stroma of several tumor entities." (PMID 30072500, 2019). "Additionally, in a melanoma tumor model, administration of a vaccine targeting tumor antigen and FAP resulted in tumor clearance as a result of antigen spreading." (PMID 30726287, 2019). "shows the increased FAP expression in CAFs surrounding the tumor cells in a stroma-high tumor." (PMID 30922247, 2019). "FAP-expressing cells also exert an immune-suppressive function in the tumor microenvironment." (PMID 31195594, 2019). "Furthermore, engineered bispecific proteins targeting the 4-1BB molecule on T-cells and tumour stroma (FAP-4-1BBL) or tumour antigen (CD19-4-1BBL) have been developed to reduce hepatotoxicity and dependency on FcγR binding (hulgG1PGLALA)." (PMID 31656546, 2019). "In addition, the use of both single-agent CAR-T as well as combined agent anti-tumor CAR-T specific for antigen erythropoietin-producing HCC A2 (EphA2) on FAP+ CAF were reported." (PMID 31540435, 2019). "Based on the pro-tumorigenic functions of tumor stroma and the strong antiviral immune responses that limit OV therapy, the destruction of CAFs by arming OVs with FAP-targeting Bispecific T-cell Engagers (BiTEs) may mitigate the key limitations of OVs." (PMID 30683154, 2019). "Further research is required to elucidate how FAP+ CAFs participate in tumor immunosurveillance." (PMID 31462327, 2019). "Therapeutically targeting FAP+ CAFs may eventually promote anti-tumor growth in CRCs with high stromal content." (PMID 30922247, 2019). "FAP expression was also increased at the invasive part compared to the tumor center." (PMID 30922247, 2019). "A recent study also reveals that FAP+PDPN+ CAFs could regulate tumor-specific cytotoxic cell motility and localization through nitric oxide synthase (iNOS)." (PMID 31462327, 2019). "Thus, cancer-associated fibroblasts differ from normal fibroblasts by providing FAP as a target with a relatively high tumor-specific expression, and FAP inhibitors (FAPIs) have already been developed as cancer drugs." (PMID 30072500, 2019).
tumor (continued). "Another approach involved the adoptive transfer of FAP-targeted chimeric antigen receptor (CAR) T cells, which killed FAP+ CAFs and induced multiple beneficial stroma alterations, leading to delayed tumor growth and survival extension in mouse models of NSCLC and PDAC." (PMID 31108941, 2019). "To determine how FAP inhibition combined with radiation resulted in tumor growth delay, we interrogated the tumor microenvironment at time points where we observed differences in tumor growth." (PMID 30726287, 2019). "FAP is a molecular target that holds great potential for tumour imaging and therapy." (PMID 30823564, 2019). "Based on these data, we observed tumor growth delay in FAP KO tumor bearing animals compared to WT tumor bearing animals receiving the same T cells suggesting that the FAP KO backgrounds conferred a tumor growth advantage when T cells were transferred into the animals." (PMID 30726287, 2019). "FAP KO animals demonstrated fewer tumor macrophages (Fig 4ivA)." (PMID 30726287, 2019). "Moreover, elevated FAP expression by CAFs can also recruit the circulating MDSCs into the tumor stroma through uPAR-FAK-DRC-JAK2-STAT3-CCL2 signaling pathway, thus resulting in immunosuppression in hepatic cancer." (PMID 31462327, 2019). "Thus, the strategy of arming oncolytic viruses with a FAP-targeting BiTE allows the continuous expression of BiTE directly in the tumor, preventing the targeting of healthy cells by the BiTE and in turn avoiding possible adverse effects." (PMID 30683154, 2019). "FAPI-21 and FAPI-46 revealed substantially improved ratios of tumor to blood, liver, muscle, and intestinal uptake and FAP-specific binding in vivo which was verified in competition experiments with a complete blocking of tumor accumulation after addition of unlabeled compound." (PMID 31659499, 2019). "Besides tumor epithelial cells (EpCAM+; epithelial cell adhesion molecule), CAFs (FAP+; fibroblast activation protein), immune cells (CD45+), and endothelial cells (CD31+) are the main cell types in ascites." (PMID 30710055, 2019). "We could detect FAP activity in the plasma of naive, 4T1 tumor bearing and cisplatin treated 4T1 tumorous animals with the following average AUC (± SEM) values from HPLC analysis: 518.5 ± 55.5 × 103, 1240.2 ± 77.9 × 103, 914.9 ± 71.7 × 103, respectively." (PMID 31881770, 2019). "In contrast, the specific depletion of FAP-positive fibroblasts either with genetic approaches and immunologic methods resulted in an inhibition of tumor growth." (PMID 31659499, 2019). "Furthermore, CAR-T cells targeting the same antigen have demonstrated different on-target, off-tumor toxicities in preclinical trials, some of which were mild, whereas some were lethal, such as targeting fibroblast activation protein-α (FAP)." (PMID 31783889, 2019). "Next, we evaluated whether tumor cytokines were different between WT and FAP KO tumors, and whether radiation influenced tumor cytokines." (PMID 30726287, 2019). "This suggests a recovery of FAP function leading to collagen cleavage and organization associated with a transient decrease in tumor size, though not due to decrease tumor cellularity (data not shown), but rather compaction of the tissue around the ECM." (PMID 30726287, 2019). "Therefore, we proceeded to evaluate the role of FAP in murine models of PDAC treated with radiation to model this unique human tumor biology." (PMID 30726287, 2019). "CAFs, which express fibroblast activation protein (FAP), contribute to immune escape via exclusion of anti-tumor CD8+ T cells from cancer cells, upregulation of immune checkpoint ligand expression, immunosuppressive cytokine production, and polarization of tumor infiltrating inflammatory cells." (PMID 30726287, 2019). "Moreover, the combination of FAP-targeted delivery of the photosensitizer with a localized photoirradiation of the tumor, allowed the selective eradication of CAF." (PMID 30871158, 2019).